INSR (insulin receptor)
Diseases named in the same sentence as INSR in open-access papers (continued):
Sharing a sentence is not in itself a finding about the gene and the disease.
migraine (5 papers, 2020 to 2025). "Two genetic studies have identified an important link between insulin receptor (INSR) gene polymorphisms and migraine." (PMID 35627115, 2022). "Several mechanisms may underlie the relationship between IR and migraines.Genetic predispositions could affect insulin receptor function, increasingsusceptibility to IR patients with migraines." (PMID 40129435, 2025). "This hypothesis is further supported by the association between migraine and polymorphisms in the insulin receptor gene." (PMID 38347465, 2024). "Some studies have shown that migraine patients exhibit impaired insulin sensitivity and elevated insulin levels, suggesting a possible role of the insulin receptor in migraine pathogenesis." (PMID 38347465, 2024). "During times of high metabolic demand, this condition has been shown to lower insulin receptor levels in neurones and astrocytes, resulting in a decrease in glucose absorption and glycogen formation, which could trigger the neuronal cell stress associated with migraine chronification." (PMID 35627115, 2022). "There have been convincing replications of many genetic associations with potential migraine genes, such as methylene-tetrahydrofolate reductase (MTHFR), insulin receptor (INSR) and estrogen receptor 1 (ESR1)." (PMID 33083518, 2020). "Some studies have shown a possible role of the insulin receptor in the pathophysiology of migraine." (PMID 38347465, 2024). "Interesting overlapping candidate genes for migraine and glucose-related traits are MTHFR, INSR, TNF, ESR1, NOS3, and PON1." (PMID 35627115, 2022). "However, an Australian study on one large family and a Finnish linkage study on 72 families found no linkage between the region of INSR and migraine with aura." (PMID 35627115, 2022).
myeloma (5 papers, 2012 to 2025). "Exclusion of other etiologies can include an autoimmune screen, anti-insulin receptor antibodies, complement levels and myeloma screen." (PMID 41476924, 2025). "Alternatively, knockdown of INSR also resulted in an increase in total IGF-1R expression in hTCEpi cells, which is consistent with the finding that the siRNA knockdown of INSR increases IGF-1R expression in human myeloma cells." (PMID 22879999, 2012).
non-small cell lung carcinoma (5 papers, 2013 to 2023). A group of at least three distinct histological types of lung cancer, including non-small cell squamous cell carcinoma, adenocarcinoma, and large cell carcinoma. "INSR, has been used as a biomarker for prognosis of non-small cell lung cancer and an INSR protein inhibitor, Zykadia, has been authorized by U.S. Food and Drug Administration (FDA) and European Medicines Agency as a treatment of advanced ALK-positive non-small cell lung cancer." (PMID 30913233, 2019).
sarcoma (5 papers, 2011 to 2024). A usually aggressive malignant neoplasm of the soft tissue or bone. "Also, the insulin receptor involves metabolic regulation and forms a hybrid receptor with IGF1R for IGF1, the latter together with IGF2, to promote the proliferation of sarcoma cells." (PMID 38338920, 2024).
acute lymphoblastic leukemia (4 papers, 2022 to 2024). Leukemia with an acute onset, characterized by the presence of lymphoblasts in the bone marrow and the peripheral blood. "Similarly, lnc-INSR was also reported to promote the differentiation of Tregs in pediatric acute lymphoblastic leukemia through enhancing Foxp3 expression via PI3K/AKT by blocking the ubiquitination site of INSR." (PMID 37637063, 2023). "In pediatric acute lymphoblastic leukemia (ALL), lnc-insulin receptor precursor (lnc-INSR) was identified to play a crucial role in promoting suppressive immune cells." (PMID 37346034, 2023). "For Example, in acute lymphoblastic leukemia (ALL), lnc- Insulin receptor (INSR) has a role in tumor growth and progression via overexpression of T regulatory cells (Treg) and decreases the percentage of cytotoxic T lymphocytes (CTLs)." (PMID 36207500, 2022).
amyloid (4 papers, 2021 to 2025). "Earlier reports show that in other models of amyloidosis, gait alterations have been seen, and here, the insulin receptor (IR)‐floxed 5×FAD mice also displayed altered ambulation." (PMID 40799120, 2025). "These behavioural improvements are likely underpinned by the observed reduction in amyloid plaque burden and normalisation of key molecular markers, including increased Bdnf expression, upregulation of the mitochondrial regulator Irs2, and modulation of insulin receptor-related pathways." (PMID 40862772, 2025).
bladder cancer (4 papers, 2017 to 2025). "Beyond these interactions, GAS5 directly modulates the activity of subsequent genetic targets, such as binding to the insulin receptor (IR) promoter to regulate its expression and promoting apoptosis in bladder cancer cells by downregulating the transcription of enhancer of zeste homolog 2 (EZH2)." (PMID 40563948, 2025).
cardiomyopathy (4 papers, 2016 to 2023). A disease of the heart muscle or myocardium proper. "The highly conserved circRNA-INSR, derived from the host gene encoding the insulin receptor, has been shown to have protective effects in doxorubicin-induced cardiomyopathy." (PMID 37272356, 2023).
Cirrhosis (4 papers, 2021 to 2025). A chronic disorder of the liver in which liver tissue becomes scarred and is partially replaced by regenerative nodules and fibrotic tissue resulting in loss of liver function. "A conundrum has been observed, where humans with cirrhosis have significantly higher kinase activity of the HSC insulin receptor, but not in hepatocytes." (PMID 40985048, 2025). "SRSF3 was found to be downregulated in human HCC samples, and recent studies showed SRSF3 was also reduced in NAFLD, NASH and cirrhosis liver samples in both human and mouse, and as a consequence, changes in the splicing of known SRSF3 target genes were observed (FN1, MYO1B, INSR, SLK)." (PMID 33716968, 2021).
diabetic cardiomyopathy (4 papers, 2014 to 2025). Diabetic cardiomyopathy is a disorder of the heart muscle in people with diabetes. "Reduced gck expression in the liver may induce diabetic cardiomyopathy by up regulating NADPH oxidase and down regulating insulin receptor and p-AMPK protein levels." (PMID 24447392, 2014). "Our results indicate that changes in the myocardium occur in the liver-specific glucokinase knockout mouse and suggest that reduced glucokinase expression in the liver may induce diabetic cardiomyopathy by up regulating NADPH oxidase and down regulating insulin receptor and p-AMPK protein levels." (PMID 24447392, 2014).
familial hyperinsulinemic hypoglycemia (4 papers, 2018 to 2023). "Other causes are possible such as islet cell hyperplasia, nesidioblastosis or antibodies to insulin or to the insulin receptor." (PMID 31448019, 2019).
generalized lipodystrophy (4 papers, 2021 to 2025). Almost complete absence of subcutaneous and/or visceral adipose tissue. "They included 65 patients with generalized lipodystrophy, 87 with partial lipodystrophy and 42 with defective insulin signaling, of whom 16 had a genetic INSR pathogenic variant, 25 had type B IR and 1 had a TBC1D4 defect." (PMID 33901270, 2021). "Individuals reported in the studies included 90 with partial lipodystrophy (72 due to LMNA mutation and 15 due to PPARG mutation), 42 with generalized lipodystrophy (21 AGPAT2, 21 BSCL2, 2 LMNA), and 19 with IR due to INSR mutation(s)." (PMID 37794082, 2023). "Of these, 185 (66%) had partial or generalized lipodystrophy (114 and 71 patients, respectively) and 65 (23%) had a primary disorder of insulin signaling, affecting the insulin receptor or components of the downstream insulin signaling cascade." (PMID 33901270, 2021).
glaucoma (4 papers, 2018 to 2025). Increased pressure in the eyeball due to obstruction of the outflow of aqueous humor. "Reduced INSR signalling has been linked to various neurological conditions, including glaucoma, and stimulating INSR signalling has been suggested as a possible therapeutic option." (PMID 40635100, 2025). "INSR was also associated with decreased risk for glaucoma, supported by tier 2 evidence." (PMID 40635100, 2025). "The protective role of INSR in glaucoma is likely mediated through pathways involved in RGC dysfunction." (PMID 40635100, 2025). "INSR was identified as a tier 2 candidate gene for glaucoma with tier 1 evidence for druggability." (PMID 40635100, 2025). "Additionally, inducing central insulin resistance in rodents using S961, a potent blocker of insulin receptors (IR), causes elevation in IOP and loss of RGCs, two significant pathological characteristics of glaucoma." (PMID 33925119, 2021). "By using a comprehensive analysis pipeline, we identified five potential therapeutic targets for glaucoma: two tier 1 genes (CPXM1 and FLT4), one tier 2 gene (INSR), and two tier 3 genes (CPZ and PXDN)." (PMID 40635100, 2025). "Thus, neuritin-insulin receptor-Akt and -ERK pathways in RGCs may be valid therapeutic targets for treatment of posttraumatic complication and glaucoma." (PMID 29973613, 2018).
glomerulosclerosis (4 papers, 2014 to 2025). A hardening of the kidney glomerulus caused by scarring of the blood vessels. "Mouse models with targeted deletion of the podocyte insulin receptor show a phenotype characterized by loss of podocytes, attenuation of the foot processes, increased albuminuria, and glomerulosclerosis." (PMID 41163811, 2025). "Recently, the insulin receptor was reported to be critically important for glomerular function in mice: podocyte-specific deletion of the Insr gene is associated with albuminuria, glomerulosclerosis and chronic kidney disease." (PMID 25358339, 2014). "Podocyte-specific insulin receptor KO mice develop evident albuminuria and severe podocyte injury, glomerular type IV collagen accumulation, glomerular basement membrane thickening, and glomerulosclerosis, recapitulating DN." (PMID 40027018, 2025).
hyperinsulinemic hypoglycemia (4 papers, 2014 to 2025). An inherited autosomal recessive syndrome characterized by the disorganized formation of new islets in the pancreas and congenital hyperinsulinism. "This case highlights the importance of considering variants in the INSR gene as a differential diagnosis in hyperinsulinemic hypoglycemia cases, even in adults." (PMID 39659391, 2024). "Hyperinsulinemic hypoglycemias resulting from variants in the insulin receptor (INSR) gene are rare but clinically important disorders." (PMID 39659391, 2024). "Gene variants in the insulin receptor gene (INSR) represent a rare yet clinically relevant cause of hyperinsulinemic hypoglycemia." (PMID 39659391, 2024). "A 35-year-old Caucasian woman known to suffer from late familial hyperinsulinemic hypoglycemia due to a well-known mutation in the insulin receptor gene has been pregnant 6 times." (PMID 25404386, 2014). "Variants in the INSR gene are rare yet clinically relevant causes of hyperinsulinemic hypoglycemia." (PMID 39659391, 2024). "However, there are also a few reported cases of variants in the INSR gene associated with hyperinsulinemic hypoglycemia." (PMID 39659391, 2024). "In our case, functional studies of the INSR nonsense variant would be required to ascertain this hypothesis, but its plausibility is underlined by previous reports of missense variants in the INSR gene being associated with hyperinsulinemic hypoglycemia." (PMID 39659391, 2024).
hypertriglyceridemia (4 papers, 2013 to 2024). A laboratory test result indicating elevated triglyceride concentration in the blood. "In this case, physical examination was puzzling, but 2 clinical features set apart the infant bearing an BSCL2 variant from the INSR group: lack of intrauterine growth restriction and hypertriglyceridemia." (PMID 38408297, 2024).
Infertility (4 papers, 2020 to 2025). "GnRH-specific InsR knockout mice are protected from obesity-associated infertility, with GnRH pulses that are comparable to lean control mice." (PMID 38131197, 2024). "InsR knockout in the pituitary or ovarian theca cells also protects female mice from high-fat diet-induced infertility, showing that elevated insulin acts across multiple systems to impair reproductive function under conditions of nutrient surplus." (PMID 38131197, 2024). "In obese fertile women, expression ofboth genes decreased significantly, but the infertile groupshowed a slight expression decrease in the INSR gene andan increased expression in the IRS-1 gene." (PMID 36273315, 2022). "Comparison of BMI ≤25 in the fertile womencompared to the infertile women showed that the expressionof the INSR gene was 10.07 times (P=0.002, 95% CI: 0.251-5.161) and IRS-1 gene was 4.31 times (P<0.0001, 95% CI:0.533-2.270) higher." (PMID 36273315, 2022). "The infertile group had lowerexpression of the INSR and IRS-1 genes in uterinetissue compared to the fertile group." (PMID 36273315, 2022). "Healthy infertile subjects showed 21.35times more expression of the INSR gene (P<0.0001, 95%CI: 0.230-0.604) than the infertile ones with diabetesand 16.82 times more expression for the IRS-1 gene(P<0.0001, 95% CI: 0.091-0.152)." (PMID 36273315, 2022). "Notably, double knockout of InsR and IGF-1 receptors in granulosa cells causes significant infertility, by impairing oocyte development and ovulation to a greater degree than knockout of either receptor alone." (PMID 38131197, 2024). "Also, fertile and infertile persons atBMI >25 had 1.78 times (P=0.042, 95% CI: 0.214-2.026)more expression of the INSR gene and 2.19 times (P<0.0001,95% CI: 0.069-0.812) more expression of the IRS-1 gene." (PMID 36273315, 2022). "In comparisonwith the fertile group, the expression of the INSR genewas 2.95 times (P=0.005, 95% CI: 0.397-4.010) higherand the IRS-1 gene was 2.92 times (P<0.0001, 95% CI:0.204-1.719) higher than that of the infertile group withthe age of ≤30." (PMID 36273315, 2022). "There was a statistically significant relationship between the expressions of INSR and IRS-1 genes in theendometrial tissue of the infertile women compared with the fertile women (P=0.002 and P=0.008, respectively)." (PMID 36273315, 2022). "In the fertile group, the expression of the INSR gene was2.61 times higher (P=0.002, 95% CI: 0.639-2.622) andthe IRS-1 gene was 2.87 times higher (P=0.008, 95% CI:0.177-1.137) than the infertile group." (PMID 36273315, 2022). "In this study, the expression levels of insulin receptor (INSR) and insulin receptor substrates-1 (IRS-1)genes in endometrial tissue of infertile women and fertile women with miscarriage in less than twenty weeks gestationfor unknown reasons were evaluated." (PMID 36273315, 2022).
ischemia (4 papers, 2013 to 2024). A hypoperfusion of the BLOOD through an organ or tissue caused by a PATHOLOGIC CONSTRICTION or obstruction of its BLOOD VESSELS, or an absence of BLOOD CIRCULATION. "In this study, we examined the histological presence of insulin-like growth factor-I (IGF-1) and insulin receptor substrate (IRS-1) in anatomically distinct brain circuits compared with morphological brain damage in a co-morbid rat model of striatal ischemia (ET1) and Aβ toxicity." (PMID 29572520, 2018). "Thus, the increased mRNA levels of insulin receptor (Insr) observed in both renin-b-overexpressing H9c2 cells have the potential to initiate the activation of the PI3K/AKT/mTOR signaling cascade, resulting in AKT-mediated cardioprotective effects during ischemia-related conditions." (PMID 35563765, 2022).
Parkinson disease (4 papers, 2016 to 2024). A progressive degenerative disorder of the central nervous system characterized by loss of dopamine producing neurons in the substantia nigra and the presence of Lewy bodies in the substantia nigra and locus coeruleus. "Several studies have described decreased INSR expression and/or attenuation of the activation states of INSR signaling molecules in affected brain regions in patients with Alzheimer’s and Parkinson’s diseases." (PMID 35444190, 2022).
adenoma (3 papers, 2021 to 2022). A neoplasm arising from the epithelium. "Investigations on INSR have shown that the isoform A is significantly higher in CRC than in normal tissues, while isoform B expression has been indicated to be reduced in adenomas compared to normal colon tissue." (PMID 36295073, 2022).
COVID-19 (3 papers, 2021 to 2024). A disease caused by infection with severe acute respiratory syndrome coronavirus 2. "In the HoIP is-a hierarchy, negative regulation of the insulin receptor signalling pathway is common in severe COVID-19." (PMID 38778394, 2024). "We identified TNF and INSR as key targets for diabetic COVID-19 patients based on our comorbid condition-specific target identification." (PMID 34067609, 2021). "Anti-TNF drugs that are given priority for repurposing in COVID-19 management and anti-INSR therapy need to be re-evaluated due to conflicting reports." (PMID 34067609, 2021).
dyslipidaemia (3 papers, 2020 to 2022). "In contrast, primary insulin signalling defects (in INSR or PIK3R1) do not result in dyslipidaemia or fatty liver." (PMID 35234134, 2022).
Huntington disease (3 papers, 2016 to 2022). Huntington disease (HD) is a rare neurodegenerative disorder of the central nervous system characterized by unwanted choreatic movements, behavioral and psychiatric disturbances and dementia. "In the PNO group, we identified canonical pathways associated with the synaptogenesis pathway, clathrin-mediated endocytosis signaling, Huntington’s disease signaling, insulin receptor signaling, and axonal guidance signaling." (PMID 35681434, 2022).
hypogonadotropic hypogonadism (3 papers, 2018 to 2023). Abnormal ovarian or testicular function due to insufficient hormonal stimulation from the hypothalamic-pituitary axis. "Animal studies confirm that mice with insulin receptor knockout exhibit hypogonadotropic hypogonadism." (PMID 37900148, 2023). "Ablation of insulin receptor (IR) from neurons results in hypogonadotropic hypogonadism in mice via central hypothalamic mechanism." (PMID 29643834, 2018).
lipid metabolism disorders (3 papers, 2023 to 2026). "Moreover, the removal of INSR in adipocytes results in severe lipid metabolism disorders." (PMID 36834919, 2023).
memory impairment (3 papers, 2023 to 2024). "Loss of tonic insulin receptor signaling in nerve terminals is believed to contribute to memory impairment." (PMID 37794263, 2024). "A reduction in brain insulin and insulin receptor (IR) may be associated with disorders involving memory impairment, such as AD." (PMID 37372995, 2023). "Liraglutide improves memory impairment in various AD models, decreasing AD-related insulin receptor (INSR), synaptic and Tau pathology in specific brain regions." (PMID 36845652, 2023).
mucopolysaccharidosis type 1 (3 papers, 2018 to 2024). The most common type of mucopolysaccharidosis. "Macromolecules conjugated to a peptidomimetic monoclonal antibody targeting the human insulin receptor (HIRMAb) have shown promise, with valanafusp alpha being developed for Mucopolysaccharidosis Type I (MPSI)." (PMID 39204177, 2024).
myocardial infarction (3 papers, 2021 to 2023). Gross necrosis of the myocardium, as a result of interruption of the blood supply to the area, as in coronary thrombosis. "Cardiomyocyte-selective insulin receptor knockout mice revealed decreased insulin signaling in cardiomyocytes without systemic metabolic disturbances, and showed worsen cardiac remodeling in respond to stress and accelerated cardiac mitochondrial dysfunction after myocardial infarction." (PMID 34604360, 2021).